IGF1R (insulin like growth factor 1 receptor)
Diseases named in the same sentence as IGF1R in open-access papers (continued):
Sharing a sentence is not in itself a finding about the gene and the disease.
Ewing sarcoma (continued). "However, the majority of Ewing's sarcoma patients express the type 1 fusion protein, while the response rate to anti-IGF-1R antibodies is considerably lower." (PMID 22022506, 2011). "Clinical trials of anti-IGF-1R antibodies have already demonstrated single-agent activity against relapsed Ewing sarcoma, with one of the largest showing 2 (13%) of 16 patients having objective responses, with another 8 (50%) having stable disease for at least 4 months." (PMID 21512587, 2011). "The involvement of this pathway may explain why some patients with Ewing's sarcoma demonstrate marked responses to anti-IGF-1R antibodies." (PMID 22022506, 2011). "Alternatively, resistance to anti-IGF-1R treatment in Ewing's sarcoma could be related to the activation of alternate signaling pathways including EGFR and IR." (PMID 22022506, 2011). "This may confound the preclinical assessment of how the expression pattern of various members of the IGF system in Ewing's sarcoma cell lines relate to responsiveness to R1507 and/or other IGF-1R inhibitors." (PMID 22022506, 2011). "Morphoproteomic analysis revealed that the mTOR pathway was activated in these two patients with advanced Ewing's sarcoma who showed response to combined IGF1R and mTOR inhibition, and the ERK pathway in the patient in whom resistance to this combination emerged." (PMID 21494688, 2011). "IGF1R mediates an autocrine loop that is de-regulated in Ewing Sarcoma (ES) cells." (PMID 21611203, 2011). "However, additional mechanisms beyond Akt/ERK regulation may also account for IGF1R targeting in modulating Ewing sarcoma chemotherapeutic responses." (PMID 38906855, 2024). "In summary, our data suggested that IGF-1R, IGF-1, IGFBP-1, and IGFBP-3 levels are associated with bone tumor malignancy, metastasis, and recurrence that might serve as biomarkers for osteosarcoma and Ewing sarcoma recurrence." (PMID 36713521, 2022). "The EWSR1-FLI1 fusion gene is thought to function as a regulator of the expression of insulin-like growth factor 1 (IGF1), and overexpression of IGF1 receptor (IGF1R) is observed in Ewing sarcoma cells; the IGF1R pathway could thus be a target in Ewing sarcoma cases." (PMID 35408900, 2022). "More recently, experiments conducted in Ewing sarcoma cells have demonstrated that IGF1R upregulation promotes resistance to CDK4/6 inhibitors suggesting that dual targeting of CDK4/6 and IGF1R may represent a synergistic combination with potential clinical implications for therapy in this disease." (PMID 33673232, 2021). "Interestingly, in Ewing sarcoma cell lines, IGF2BP3-mediated IGF1R loss is compensated by the activation of an IR-A/IGF2 autocrine loop, which determines higher sensitivity to the dual IGF1R/IR inhibitor OSI-906." (PMID 33673232, 2021). "However, gene signatures associated with response to robatumumab in tissues from Ewing sarcoma patient responders, non-responders and controls, identified genes were associated with mTOR and Akt action but not the IGF1R and IGF1." (PMID 34440844, 2021). "Therefore, the development of IGF1R-targeted therapies sparked much excitement, given impressive responses of heavily pre-treated Ewing sarcoma patients in early clinical trials and a broad molecular basis supporting IGF1R as a tumor-driving RTK in this sarcoma." (PMID 32272784, 2020). "Ewing’s sarcoma cells cultured on 3D electrospun PCL scaffolds showed higher expression and activation of insulin-like growth factor-1 receptor (IGF-1R), as well as higher expression of proteins associated with resistance to IGF-1R therapy, compared to 2D mono-culture." (PMID 32967150, 2020). "Additionally, the blockage of IGF-1R signaling has been shown to enhance chemotherapy response in preclinical studies of several cancer types including pancreatic and non small-cell lung cancers as well as Ewing's sarcoma." (PMID 27127884, 2016).
Ewing sarcoma (continued). "Hence, future studies are warranted to determine whether IGF1R-overexpressing Ewing sarcomas are more sensitive to BET inhibitors than Ewing sarcomas independent on the IGF1R/AKT pathway." (PMID 27259270, 2016). "Interestingly, IGF-1R inhibition seems promising in a subset of patients with Ewing sarcoma." (PMID 26563243, 2016). "Anti-IGF1R therapies have exhibited promising preclinical activities in Ewing sarcoma models, but appear to be inadequate to induce sustained clinical response either as monotherapy or in combination with mTOR inhibitors, in part due to toxicity of blocking IGF1R signaling in normal tissues." (PMID 27259270, 2016). "For example, Ewing sarcoma cells cultured in porous 3D electrospun poly(ε-caprolactone) scaffolds were not only more resistant to traditional cytotoxic drugs than cells in 2D monolayer cultures but also exhibited remarkable differences in the expression pattern of the IGF-1R/mTOR pathway." (PMID 26779435, 2015). "Additionally, we characterized the expression and activation of the IGF-1R signaling pathway in Ewing sarcoma stem-like cells (ESSCs), a population of tumor cells that are relatively resistant to chemotherapy, in order to investigate a potential reservoir for resistance to anti-IGF-1R therapy." (PMID 23431249, 2013). "Also, combination of IGF-1R and mTOR inhibition showed clinical benefits in Ewing's sarcoma." (PMID 23663564, 2013). "These inhibitors can be potentially used in Ewing sarcoma treatment, given the fact that the IGF1/IGF-1R signaling pathway plays a significant role in Ewing sarcoma malignancy." (PMID 37830183, 2024). "When the trial was designed, IGF1R inhibitors had shown a 5%–15% response rate in Ewing sarcoma, but a short median PFR, for example, 7.5 weeks in a Ewing sarcoma subset of a phase II trial of cixutumumab and temsirolimus in metastatic sarcomas." (PMID 35950293, 2023). "In PDX models of Ewing sarcoma, treatment with the BRD4 inhibitor NHWD870 and the IGF1R inhibitor BMS754807 results in substantial and durable anticancer effects, while monotherapy was much less effective." (PMID 38135679, 2023). "Accordingly, under basal conditions, CDS PDX-derived cell lines displayed higher constitutive expression of IGF1R and increased activation of the AKT pathway than did Ewing sarcoma PDX-derived cell lines." (PMID 34903601, 2022). "In the IGF1R pathway, we find increased dependency on IGF2BP1, IGF1R, IRS1, and IRS2 in neuroblastoma, Ewing’s sarcoma, pancreas, myeloma, or rhabdomyosarcoma." (PMID 35382456, 2022). "These include correlations between IGF2BP1 and IGF1R (R = 0.48) in Ewing’s sarcoma and between IGF2BP1 and IRS2 dependencies (R = 0.32) in Ewing’s sarcoma and neuroblastoma." (PMID 35382456, 2022). "IGF-1R signaling has an effect on endogenous IGF-1, and the fusion gene EWS-FLI1 is present in Ewing sarcoma." (PMID 35680570, 2022). "Data from the current study showed over-expression of IGF-1R, IGF-1, IGFBP-1, and 3 in local tumor tissues and serum of patients with Ewing sarcoma." (PMID 36713521, 2022). "The IGF-1R protein over-expression was detected in osteosarcoma tumors compared to Ewing sarcoma (P=0.03) and GCT (P < 0.0001), also Ewing sarcoma tumors compared to GCT (P < 0.0001)." (PMID 36713521, 2022). "Inhibitors of Insulin-like growth factor 1 receptor (IGF1R) and poly-(ADP-ribose) polymerase (PARP1) are also under investigation for treatment of Ewing’s sarcoma." (PMID 34683845, 2021). "At the preclinical level, expression levels of the RNA-binding protein IGF2BP3, in combination with the IGF1R/IR ratio, were suggested as putative predictor of response to linsitinib (OSI-906) in Ewing sarcoma cells." (PMID 34440844, 2021). "Accordingly, Ewing sarcoma cells with decreased expression of IGF2BP3 and the IGF1R, but increased compensatory expression of the IR, displayed higher sensitivity to OSI-906 compared to cells expressing high levels of IGF2BP3." (PMID 34440844, 2021).
Ewing sarcoma (continued). "In Ewing sarcoma, transcriptional up-regulation and autocrine activation of the IGF2/IR-A axis represents a major mechanism of resistance to anti-IGF1R agents." (PMID 33673232, 2021). "A combinatorial approach with anti-IGF1R mAb ganitumab and the CDK4/6 inhibitor palbociclib is currently under investigation in Ewing sarcoma (NCT04129151)." (PMID 34440844, 2021). "In Ewing sarcoma, we identified RON among RTKs conferring resistance to insulin-like growth factor-1 receptor (IGF1R) targeting." (PMID 32272784, 2020). "The insulin-like growth factor-1 receptor (IGF1R) is a receptor commonly overexpressed and overactivated in a variety of cancers, including Ewing sarcoma, and promotes cell growth and survival." (PMID 33260481, 2020). "In Ewing sarcoma, lower IGF-1 circulating levels were found in patients with metastatic disease, while in a cohort of 57 patients, a relationship between high IGF-1R and IGF-1 expression and favorable prognosis was found." (PMID 28545426, 2017). "Promising phase I data, particularly in Ewing sarcoma, led to the phase II evaluation of IGF1 receptor (IGF1R) inhibitors in multiple sarcoma subtypes." (PMID 26402468, 2015). "Here, we report that IGF1R (15/15) and ROR1 (11/15) were highly expressed in sarcoma cell lines including Ewing sarcoma, osteosarcoma, alveolar or embryonal rhabdomyosarcoma, and fibrosarcoma." (PMID 26173023, 2015). "However, despite the numerous potential candidates for combination therapy with anti-IGF-1R antibodies, it is necessary to take into account the mixed results of preclinical and clinical studies as well as the modest biological evidence underlying IGF-1R as a target for Ewing sarcoma therapy." (PMID 23431249, 2013). "Finally, we critically review the literature on IGF-1R in ES, in an effort to shed light on the recently published outcomes of targeting the IGF-1 receptor in patients with Ewing sarcoma." (PMID 23431249, 2013). "In Ewing sarcoma, characterized by EWS/FLI-1 translocation, enhanced IGF-1R activity has been observed." (PMID 22415797, 2012). "In phase I trials, IGF-1R inhibitors (R1507, AMG479, CP-751, 871) showed sustained remission in patients with Ewing sarcoma." (PMID 22577336, 2012). "A subset of patients with Ewing's sarcoma have remarkable responses to insulin-like growth factor-1 receptor (IGF-1R) inhibitors, including the fully human anti-IGF-1R antibody, R1507." (PMID 22022506, 2011). "IGF1R chaperoning by HSP90 and its possible relationship with resistance to IGF1R targeting has been shown in Ewing's sarcoma." (PMID 21437217, 2011). "PubMed was searched using a combination of Medical Subject Headings (MeSH) and free-text terms for sarcoma and Ewing sarcoma together with variations of IGF-1, IGF-1R, and relevant therapeutic agents (ganitumab, linsitinib, cixutumumab, robatumumab, figitumumab, dalotuzumab)." (PMID 41347090, 2025). "Several of these Ewing sarcoma tumor cell–expressed genes have been previously studied in Ewing sarcoma [AXL, WNT5A, IGF-1R, TNFRSF10B (TRIAL-R2/DR5)], and have been described as potential targets in Ewing sarcoma and/or to be involved in Ewing sarcoma tumor cell migration/metastatic potential." (PMID 37823774, 2023). "The IGF‐1R/mTOR pathway is frequently activated in sarcomas and other solid tumors, so it is considered an attractive target for Osteosarcoma (OS) and Ewing sarcoma (ES) since it represents the aggregation of multiple chemical and mechanical signaling mechanisms." (PMID 36807772, 2023). "In Ewing sarcoma cell lines and patient-derived xenograft (PDX) lines, AKT pathway activation protects Ewing sarcoma cells against BRD4 inhibitors, and IGF1R inhibitors and mTOR inhibitors suppress AKT pathway activation and synergistically enhance cancer cell sensitivity to BRD4 inhibitors." (PMID 38135679, 2023).
Ewing sarcoma (continued). "While responses were seen in metastatic Ewing sarcoma using IGF1R inhibitors, Ewing sarcoma patients did not derive benefit from the use of IGF1R inhibitors as part of primary therapy." (PMID 35950293, 2023). "Regarding Ewing sarcoma, both metastatic tumors (0.3280) and recurrent tumors (0.3280) expressed a significantly higher level of IGF-1R compared to non-metastatic (0.1168) (P < 0.05) and non-recurrent tumors (0.1234) (P < 0.001), respectively." (PMID 36713521, 2022). "Although cold antibody was only modestly effective in Ewing sarcoma and not in osteosarcoma, chelation of the alpha emitter 225Ac can arm the anti-IGF1R antibody to become a potent alpha emitter." (PMID 36457575, 2022). "This suggests that the IGF-1R signal may have a synergistic effect on fusion gene EWS-FLI1, thus driving the occurrence of Ewing sarcoma." (PMID 35680570, 2022). "The IGF-1R protein level in chemotherapy-received osteosarcoma and Ewing sarcoma tumors showed no remarkable difference compared to their opposite counterparts." (PMID 36713521, 2022). "The lack of response to IGF agents in Ewing sarcoma likely depends on an aquired resistance mechanisms developed by these cells to adapt to IGF1R depletion." (PMID 34440844, 2021). "Taking into account that IGF2BP3 sustains IGF1R expression as well, we can speculate that co-targeting the IGF axis and CXCR4 in Ewing sarcoma cells expressing high levels of IGF2BP3 might represent a valuable therapeutic option." (PMID 34440844, 2021). "Accordingly, linsitinib, which blocks both the IGF1R and IR, was evaluated in Ewing sarcoma patients but no response was evidenced (NCT02546544)." (PMID 34440844, 2021). "Moreover, in the same study, in Ewing sarcoma, exposure to PU-H71 resulted in depletion of critical proteins, including AKT, pERK, Raf-1, c-MYC, c-KIT, IGF1R, hTERT, and EWS-FLI78." (PMID 32895397, 2020). "Insulin-like growth factor-1 receptor (IGF1R) inhibitors are effective in preclinical studies, but so far, no convincing benefit in clinical studies has been observed, except in some rare cases of sustained response in Ewing sarcoma patients." (PMID 33260481, 2020). "Insulin-like growth factor 1 receptor (IGF-1R) and tyrosine kinase orphan-like receptor 1 (ROR1) are highly expressed in various sarcoma cell lines such as alveolar or embryonal rhabdomyosarcoma, Ewing sarcoma, fibrosarcoma and osteosarcoma." (PMID 33207697, 2020). "Unfortunately, no convincing benefit of IGF1R pathway inhibitors has been found in these studies, except in some rare cases of a sustained response in patients with Ewing sarcoma and adrenocortical carcinoma." (PMID 33260481, 2020). "Despite encouraging results in early clinical trials, IGF-1R inhibitors have not proved to have useful single agent activity in patients with cancer, with the possible exception of Ewing sarcoma." (PMID 31416218, 2019). "Based on Ewing sarcoma model and EWS-Fli translocation, leading to dysregulation of insulin growth factor 1 (IGF1) receptor and dependence on IGF1, humanized monoclonal antagonist IGF1 receptor (IGF1R) antibodies have been developed." (PMID 28491276, 2017). "Next, expression levels of eight EWS-FLI1 associated target genes (GLI1, NEX2.2, CyclinD, c-MYC, NR01B, IGF1R, EZH2, and CD99) which were known to be upregulated, and three genes (FOXO1, IGFBP3, and LOX) known to be down regulated in Ewing’s sarcoma was assessed." (PMID 28775288, 2017). "Our previous study showed that cyclin-dependent kinase 4/6 (CDK4/6) and insulin-like growth factor-1 receptor (IGF-1R) inhibitors were effective on the Ewing’s sarcoma PDOX, but not doxorubicin, similar to the patient’s resistance to doxorubicin." (PMID 29262551, 2017). "In addition, JQ1 significantly decreased phosphorylation of IGF1R and AKT in multiple Ewing sarcoma cell lines, including 5838 that expresses EWS-ERG." (PMID 27259270, 2016).
Ewing sarcoma (continued). "In support of functional importance of PTEN loss in Ewing Sarcoma, we show that re-introduction of PTEN into two different PTEN-negative Ewing Sarcoma cell lines results in downregulation of PI3K pathway activity, and sensitization to the IGF-1R small molecule inhibitor OSI-906." (PMID 25603314, 2015). "The latest developments in Ewing’s sarcoma tend to show that Insulin-like Growth Factor 1 Receptor (IGF1R) targeting agents are promising, but none was efficient enough to lead to a phase III trial." (PMID 25420707, 2014). "In the clinic, these IGF1R antibodies have produced compelling proof-of-principle data that implicate an important role for IGF signaling in numerous tumor types including, but not limited to, NSCLC and Ewing's Sarcoma." (PMID 19732452, 2009). "A phase III Children’s Oncology Group randomized controlled trial of the IGF-1R antibody ganitumab in combination with standard of care chemotherapy for children with metastatic Ewing sarcoma unfortunately showed no benefit in event-free survival and increased toxicity in the experimental arm." (PMID 40983796, 2025). "Also, the IGF-1R protein level was significantly elevated in metastatic and recurrent Ewing sarcoma tumors compered to non-metastatic (P=0.0008) and non-recurrent tumors (P < 0.0001)." (PMID 36713521, 2022). "Chromosomal rearrangements leading to oncogenic fusion like TMPRSS2-ERG, EWS-WT1, and PAX3-FKHR, sustain IGF1R expression in prostate cancer, desmoplastic small cell tumor and alveolar rhabdomyosarcoma, respectively, while EWS-FLI favors IGF1 but inhibits IGFBP3 transcription in Ewing sarcoma." (PMID 34440844, 2021). "In the context of bone tumors, a recent study suggested that the dual inhibition of CDK4/6 and of IGF-1R may be a candidate synergistic combination for the clinical application in Ewing sarcoma, since CDK4/6 drug resistance is mediated by the activation of IGF-1R signaling." (PMID 32326412, 2020). "However, with the significant effects of IGF1R co-targeting not observed in MET-negative Ewing sarcoma counterparts, this setting appeared unsuitable to pursue potential RON−IGF1R−MET interaction in rhabdomyosarcoma." (PMID 32272784, 2020). "Whilst hoping that these few success cases could offer important insight into the mechanisms, anti-IGF-1R therapy is still yet to reach clinical practice in the treatment of Ewing’s sarcoma patients, nor any other cancer types." (PMID 31600876, 2019). "Insulin-like growth factor 1 receptor (IGF-1R) was a candidate as a treatment target of Ewing sarcoma, and early-phase clinical trials of IGF-1F inhibitors, especially of figitumumab, showed a modest response among recurrent/metastatic Ewing sarcoma patients, including complete remission." (PMID 29510588, 2018). "We also noticed that Ewing sarcoma cell lines expressing low levels of IGF1R, such as A673, were less sensitive to JQ1 in comparison to IGF1R-overexpressing lines, underscoring the significance of the IGF1 autocrine mechanism as a key target of BET inhibitors in Ewing sarcoma." (PMID 27259270, 2016). "It is worth noting that the IGF1R-low line A673 had the highest IC50 value among these lines, thus supporting the hypothesis that the IGF1 autocrine loop is a key target of BET inhibitors in Ewing sarcoma." (PMID 27259270, 2016). "Three Ewing sarcoma patients had responses to anti-IGF-1R therapy with or without mTOR inhibition." (PMID 27486883, 2016). "IGF receptor targeting alone may not be effective since Ewing sarcoma cells can switch to alternative signaling pathways from IGF-1R to IR-A to maintain sustained activation of ERK1/2." (PMID 22577336, 2012). "One, though likely not exclusive, interacting partner is IGF1R, a prominent RTK in Ewing sarcoma biology." (PMID 32272784, 2020).